ULK1 (unc-51 like autophagy activating kinase 1)
Diseases named in the same sentence as ULK1 in open-access papers (continued):
Sharing a sentence is not in itself a finding about the gene and the disease.
pancreatic ductal adenocarcinoma (10 papers, 2015 to 2025). An infiltrating adenocarcinoma that arises from the epithelial cells of the pancreas. "PVT1 expression levels were positively associated with that of ULK1 in pancreatic ductal adenocarcinoma tissues." (PMID 33050642, 2020). "Researchers wanted to understand how ULK1 affects cancer progression, especially in pancreatic ductal adenocarcinoma." (PMID 41408407, 2025). "Although the cellular functions of ULK1 have been studied in several diseases, direct evidence of the role of ULK1 on the tumor progression of pancreatic ductal adenocarcinoma (PDAC) remains largely unexplored." (PMID 41408407, 2025). "While Atg5 and Atg7 are well established core autophagy genes, the role of Unc-51-like kinase 1 (ULK1)—a key autophagy initiator—remains poorly understood in pancreatic ductal adenocarcinoma (PDAC)." (PMID 41408407, 2025). "Further study showed that PVT1 functioned as an miRNA sponge of miR-20a-5p and restored the expression of ULK1 in the progression of pancreatic ductal adenocarcinoma." (PMID 33050642, 2020). "Furthermore, we observed significant inverse correlation between NEDD4L and ULK1 levels in the pancreatic regions from spontaneous pancreatic ductal adenocarcinoma (PDAC) mouse model driven by KrasLSL-G12D/+; Trp53LSL-R172H/+; Pdx1-Cre (KPC)." (PMID 31959741, 2020). "Furthermore, pancreatic ductal adenocarcinoma cells, whose growth depends on high basal autophagy, possess stronger basal phosphatase activity towards ULK1 and require ULK1 for sustained anchorage-independent growth." (PMID 26310906, 2015). "In pancreatic ductal adenocarcinoma, lncRNA PVT1 acts as a sponge to regulate miR-20a-5p and thus affects the expression of unc-51-like-kinase 1 (ULK1), which is a key molecule of autophagy initiation." (PMID 32429086, 2020).
Parkinson disease (10 papers, 2010 to 2025). A progressive degenerative disorder of the central nervous system characterized by loss of dopamine producing neurons in the substantia nigra and the presence of Lewy bodies in the substantia nigra and locus coeruleus. "USP24 has been reported to inhibit autophagy in neurons by increasing the degradation of ULK1 to repress the human induced-pluripotent stem cell (iPSC) differentiation into dopaminergic neurons, which is involved in Parkinson’s disease (PD)." (PMID 38491202, 2024). "MiR-3473b can regulate the secretion of pro-inflammatory mediators by targeting TREM2/ULK1 expression, thereby modulating the role of autophagy in the pathogenesis of Parkinson’s disease (PD) inflammation." (PMID 39239635, 2024). "Recently, we have demonstrated ULK1.DN-mediated protection of dopaminergic nigral neurons and nigro-striatal projections against MPTP-induced degeneration in a mouse model of Parkinson’s disease." (PMID 32341448, 2020). "In Parkinson’s disease, autophagy activation via agents such as metformin has shown neuroprotective effects by activating the AMPK/ULK1/PINK1/Parkin pathway, thereby enhancing autophagy and mitophagy, promoting mitochondrial clearance, and reducing neuronal apoptosis in experimental models." (PMID 41007413, 2025). "Additionally, the miR-3473b targets the triggering receptor expressed on myeloid cells 2 (TREM2) and Unc-51 like autophagy activating kinase 1 (ULK1) to regulate the inflammatory response, such as the secretion of TNF-α and IL-1β, in Parkinson's disease." (PMID 36572876, 2022). "This increase is mediated by the protein ULK1, suggesting that the process may be independent of PRKN,128 despite higher activation of “PINK1 accumulation” in the simulation for the parkinsonism cohort." (PMID 39429779, 2024).
diabetic nephropathy (9 papers, 2021 to 2025). "AMPK phosphorylation was also followed by upregulation of ULK1, enhancement of autophagy, and decrease in oxidative stress, podocyte loss, fibrosis, and albuminuria in a mouse model of diabetic nephropathy." (PMID 36818747, 2023). "TSJ or metformin markedly upregulated the level of nephrin and podocin, accompanied by evident enhancement of podocyte autophagy and activation of p-AMPK/p-ULK1 signaling in the diabetic nephropathy." (PMID 35449816, 2022). "Other research has shown that the phosphorylation of ULK‐1 was also reduced when autophagy was enhanced in diabetic nephropathy." (PMID 33459523, 2021). "A recent study of immune infiltration analysis by CIBERSORT algorithms revealed that in diabetic nephropathy, ULK1 had a positive correlation with neutrophils and a negative correlation with M1 and M2 macrophages, further supporting the importance of ULK1 in regulating an inflammatory response." (PMID 38672681, 2024). "Furthermore, in diabetic nephropathy (DN), Dong, Zheng also highlights that the downregulation of ULK1 is responsible for autophagy impairment in DN." (PMID 38099142, 2023). "This indicates that TSJ may enhance podocyte autophagy activity through AMPK protein and downstream ULK1 signal and protect and prevent podocyte damage during diabetic nephropathy." (PMID 35449816, 2022). "ULK1 is a potential biomarker for DN and may influence the development of diabetic nephropathy by regulating mitophagy." (PMID 36743936, 2022). "Therefore, TSJ may enhance podocyte autophagy to relieve diabetic nephropathy through modulation of p-AMPK/p-ULK1 signaling, which has important application prospects in the clinical treatment of diabetic kidney damage in the future." (PMID 35449816, 2022). "In summary, this study established a rat diabetic nephropathy model and found that TSJ can enhance podocyte autophagy activity through AMPK protein and downstream ULK1 signal, reduce podocyte damage, and then play a protective role in the kidneys of diabetic nephropathy rats." (PMID 35449816, 2022).
neuroblastoma (9 papers, 2015 to 2026). Neuroblastoma (NB) is the most common solid, extracranial childhood tumor. "Collectively, these findings demonstrate that 4-MD engages multiple, non-redundant cell death pathways through coordinated ROS-MAPK-AMPK/mTOR/ULK1 signaling, highlighting its potential to overcome therapeutic resistance in heterogeneous neuroblastoma cells." (PMID 41827863, 2026). "In contrast, a kinase-dead ULK1 mutant suppressed growth and metastasis and increased survival in a neuroblastoma xenograft mouse model." (PMID 35365653, 2022). "Nonetheless, these results are consistent with PAM restricting ULK1 levels in human neuroblastoma cells." (PMID 31676756, 2019). "In another study, Chen and coworkers proposed that ULK1 could inhibit p70S6K in starvation-induced autophagy of neuroblastoma SH-SY5Y cells and further identified that miR-4487 and miR-595 were novel ULK1-targeting miRNAs." (PMID 28459042, 2017). "Thus, in this study, we computationally constructed the ULK1-regulated autophagic kinase subnetwork in PD and further identified ULK1 able to negatively regulate p70S6K in starvation-induced autophagy of neuroblastoma SH-SY5Y cells." (PMID 26183158, 2015). "To investigate this possibility, we quantified the induction of ULK1 complex translocation and autophagy elicited by increased C9orf72S or C9orf72L expression in Rab1a siRNA‐treated HeLa and SH‐SY5Y neuroblastoma cells." (PMID 27334615, 2016). "Utilizing ULK1-knockout neuroblastoma cells, we have identified that ULK1 is not essential for productive AP formation induced by PHEV." (PMID 34287052, 2021).
viral infection (8 papers, 2017 to 2025). "Remarkably, the pharmacological inhibition of receptor-mediated viral entry by the ULK1 activator suggested that this downstream kinase also regulates flavivirus entry, revealing a previously unrecognised role in the viral infection process." (PMID 40072063, 2025). "RIP2 also regulated mitophagy in a kinase-dependent manner by phosphorylating the mitophagy inducer ULK1 during viral infection." (PMID 29692779, 2018). "Induction of autophagy by cellular stress or viral infections is governed by a set of kinases including AMPK and ULK1, which promote autophagy induction, while mTOR and CK2 negatively regulate ULK1 activity." (PMID 39289189, 2024). "Other genes that were down-regulated with viral infection (GOLGA2, IFI16, WDR81, HK2, SQSTM1, ULK1) remained down-regulated with NIC treatment (with and without virus)." (PMID 37901834, 2023).
Myocardial fibrosis (7 papers, 2022 to 2025). "This leads to the decreased phosphorylation of ULK1 at the Ser757 site, inhibiting the downstream autophagy pathway and exacerbating myocardial fibrosis." (PMID 40002810, 2025). "The activation of ULK1 proteins induces activation of hepatic mitophagy activity, which in turn attenuated isoproterenol-induced myocardial fibrosis in mice." (PMID 35745140, 2022). "AMPK initiates autophagy by phosphorylating ULK1 (autophagy initiation kinase), which promotes autophagosome formation, thereby reducing ECM overaccumulation and exerting a protective effect against myocardial fibrosis." (PMID 40002810, 2025).
Alzheimer disease (6 papers, 2019 to 2026). A progressive, neurodegenerative disease characterized by loss of function and death of nerve cells in several areas of the brain leading to loss of cognitive function such as memory and language. "Moreover, pimozide has been shown to reduce aggregation of tau protein as well as memory loss in Alzheimer’s disease models via activation of the Adenosine Monophosphate-Activated Protein Kinase (AMPK)-ULK1 axis." (PMID 31959760, 2020). "KLHL20 is a related CUL3-dependent ubiquitin ligase linked to autophagy, cancer, and Alzheimer's disease that promotes the ubiquitination and degradation of substrates including DAPK1, PML, and ULK1." (PMID 31279627, 2019).
Cerebral ischemia (6 papers, 2015 to 2023). Restriction of arterial blood supply to the brain associated with insufficient oxygenation to support the metabolic requirements of the tissue. "Multiple studies also demonstrated the role of puerarin against cerebral ischemia injury by attenuating autophagy through the activation of the APMK-mTOR-Unc-51-like kinase 1 (ULK1) signaling pathway." (PMID 35855345, 2022). "The in vivo and vitro results thus reveal that DOR activation by DADLE enhances neuronal autophagy to protect against cerebral ischemia by activating the AMPK/mTOR/ULK1 signaling pathway." (PMID 32549974, 2020).
Crohn disease (6 papers, 2011 to 2025). A gastrointestinal disorder characterized by chronic inflammation involving all layers of the intestinal wall, noncaseating granulomas affecting the intestinal wall and regional lymph nodes, and transmural fibrosis. "Two SNPs in ULK1, rs12303764 and rs3923716 were significantly associated with Crohn's disease susceptibility." (PMID 39883213, 2024). "Polymorphisms in ULK1 result in defective macrophage-mediated AIEC clearance in Crohn's disease patients." (PMID 39883213, 2024). "Polymorphisms in members of the ULK1/2 kinase complex have been associated with a variety of pathologies related to immune system dysfunction: Crohn’s disease susceptibility, tuberculosis and ankylosing spondylitis." (PMID 38002079, 2023). "As research progresses, more and more autophagy-related Crohn's disease susceptibility genes have been identified, such as IRGM, ULK1, LRRK2, TLR4, etc.." (PMID 39883213, 2024). "A number of GWAS analyses have linked SNPs in autophagy-related genes to susceptibility for autoimmune diseases, e.g., autophagy-specific gene 1 (ATG5) in systemic lupus erythematosus and unc-51-like kinase 1 (ULK1) in Crohn’s disease." (PMID 23439554, 2013). "The gene ULK1 is an excellent candidate for Crohn's disease (CD) due to its role in autophagy." (PMID 22536218, 2012). "Finally, a recent study specifically examining autophagy gene loci found a SNP in Unc-51-like kinase-1 (ULK1) to be present more frequently in Crohn’s disease patients." (PMID 21994779, 2011). "The blood monocyte-derived macrophages (BMDMs) from patients with Crohn disease exhibit increased AIEC replication compared to those from healthy individuals, and this defect in AIEC clearance is linked to the Crohn disease-associated variants in the autophagy-related genes IRGM and ULK1." (PMID 40910070, 2025).
Huntington disease (6 papers, 2013 to 2019). Huntington disease (HD) is a rare neurodegenerative disorder of the central nervous system characterized by unwanted choreatic movements, behavioral and psychiatric disturbances and dementia. "This is accompanied by reduced autophagy (accumulation of p62) as the consequence of increased ZBTB16 expression and reduced ULK1 activity, as we have previously observed in Huntington’s disease (HD)." (PMID 29631635, 2018). "We also show that ATG14-associated Vps34 activity and ULK1-mediated phosphorylation of ATG14 and Beclin 1 are compromised in the Q175 mouse model of Huntington’s disease." (PMID 27938392, 2016). "Importantly, HTT, whose expression is abrogated by the pQ expansion in Huntington’s disease, was recently found to facilitate selective autophagy by acting as a scaffold between autophagy adaptor p62/SQSTM1 and core autophagy molecules such as Atg1/ULK1 and Atg8/LC3 proteins." (PMID 28737703, 2017).
Hyperglycemia (6 papers, 2015 to 2025). An increased concentration of glucose in the blood. "Studies have shown that ULK1 can inhibit the activity of the NLRP3 inflammasome in the pyroptosis pathway potentially aiding in mitigating the harmful effects of hyperglycemia-induced oxidative stress and inflammation in diabetic wounds." (PMID 40750912, 2025). "Concurrently, hyperglycemia‐associated metabolic excess reduces AMPK activation, which would otherwise promote autophagy by phosphorylating ULK1 at distinct activating residues." (PMID 40660790, 2025). "However, exposure to hyperglycemia leads to activation of mTORC1 which, in turn, phosphorylates and inactivates ULK1, thus preventing initiation of autophagosome formation." (PMID 30467302, 2018). "In addition, hyperglycemia was also demonstrated to promote macrophage pyroptosis and pro-inflammatory factor secretion by activating mTOR/4EBP1 and decreasing downstream ULK1 activity and autophagy flux, which in turn, aggravates alveolar bone resorption in periodontitis." (PMID 37298150, 2023). "LC3II/LC3I ratio was significantly decreased due to acute hyperglycemia, however, other autophagy-related proteins such as Beclin-1, total and Triton X-100-insoluble SQSTM1/p62, phospho-ULK1 (Ser555), ATG7 and BNIP3 were unchanged in AHG group." (PMID 26581389, 2015). "In spite of a decreased LC3II/LC3I ratio, other markers of autophagy, such as ATG7, ULK1 phopsphorylation, Beclin 1 and SQSTM1/p62, were not modulated by acute hyperglycemia." (PMID 26581389, 2015).
ischemic stroke (6 papers, 2015 to 2023). A stroke disorder caused by obstruction of blood flow to the brain, due to thrombotic (local blood clot formation) or embolic (due to a blood clot or other material traveling from another site) event. "Altogether, these results suggest that the neuroprotective effects of microglial PGC-1α may be mediated by autophagy and mitophagy through ULK1 after ischemic stroke." (PMID 33771213, 2021). "Finally, pharmacological inhibition and genomic knockdown of ULK1 were performed to estimate the role of ULK1 in mediating mitophagic activity after ischemic stroke." (PMID 33771213, 2021). "The expression of autophagosome membrane makers, such as Unc-51-like kinase 1 (ULK1), autophagy-related gene 13 (Atg13) also may be reduced by EA treatment with 1–20 Hz for 3 days after ischemic stroke." (PMID 30618558, 2018).
liver fibrosis (6 papers, 2020 to 2026). "Taken together, our findings highlight m6A-dependentULK1 as an essential regulator of HSC autophagy and reveal that ULK1 is a novel potential therapeutic target for hepatic fibrosis treatment." (PMID 39175431, 2024). "Overall, the findings indicated that anti-PCSK9 treatment improved liver fibrosis by regulating hypoxia-induced autophagy in hepatocytes through the AMPK/mTOR/ULK1 signaling pathway." (PMID 37466835, 2023). "Anti-PCSK9 treatment alleviates liver fibrosis by regulating hypoxia-induced autophagy in the hepatocytes through AMPK/mTOR/ULK1 signaling pathway." (PMID 37466835, 2023). "Subsequent research has indicated that anti-PCSK9 treatment may hold the potential to mitigate liver fibrosis by modulating the AMPK/mTOR/ULK1 signaling pathway, thus reducing hypoxia-induced autophagy in hepatocytes." (PMID 39090671, 2024). "Our study indicated that m6A modification may be a novel and important posttranscriptional regulator of HSC autophagy and that ULK1 may be a potential therapeutic target for hepatic fibrosis treatment." (PMID 39175431, 2024). "Our findings provide new insight showing that targeting the FTO/ULK1 axis may be a promising strategy for clinical anti-liver fibrosis therapy." (PMID 39175431, 2024). "In summary, this study demonstrated that the m6A demethylase FTO promotes HSC autophagy by targeting ULK1, resulting in HSC activation and ultimately leading to hepatic fibrosis." (PMID 39175431, 2024).
myocardial ischemia (6 papers, 2019 to 2024). A disorder of cardiac function caused by insufficient blood flow to the muscle tissue of the heart. "Furthermore, EMPA treatment was reported previously to induce the autophagy process in a cardiac ischemia/reperfusion animal model via activation of the AMPK-α1/ULK1/FUNDC1 pathway." (PMID 38929110, 2024). "During acute myocardial ischemia, autophagy has been shown to confer cardioprotection, as deletions/mutations of proteins involved in the formation of the autolysosome (DRAM2, Ulk1, Atg7) either induce baseline cardiac dysfunction, or exacerbate MI pathophysiology." (PMID 35614179, 2022). "In addition to myocardial ischemia, ULK1-FUNDC1-mediated mitophagy is also the mechanism of renoprotection using ischemia preconditioning in ischemic acute kidney injury." (PMID 35959490, 2022). "Current studies have shown that during myocardial ischemia, due to reduced ATP production, Adenosine 5′-monophosphate (AMP)-activated protein kinase (AMPK) is activated, resulting in mTOR inactivation, thereby catalyzing UNC-51-like kinase 1 (ULK1)-induced autophagy." (PMID 36091830, 2022).